DOCK9-DT (DOCK9 divergent transcript)
Synonyms: formerly DOCK9-AS2
Gene: Long non-coding RNA gene on chromosome 13 (99,087,819 to 99,088,625, forward strand). Ensembl gene ENSG00000260992.
Diseases named in the same sentence as DOCK9-DT in open-access papers:
DOCK9-DT is named in the same sentence as 2 diseases in open-access papers, as found by Europe PMC text mining. Sharing a sentence is not in itself a finding about the gene and the disease.
DOCK9-DT shares sentences with these, for which no sentence is quoted: thyroid carcinoma (1 paper); tumor (1).